RPS9 (ribosomal protein S9)
Description:
Component of the small ribosomal subunit. The ribosome is a large ribonucleoprotein complex responsible for the synthesis of proteins in the cell. Part of the small subunit (SSU) processome, first precursor of the small eukaryotic ribosomal subunit. During the assembly of the SSU processome in the nucleolus, many ribosome biogenesis factors, an RNA chaperone and ribosomal proteins associate with the nascent pre-rRNA and work in concert to generate RNA folding, modifications, rearrangements and cleavage as well as targeted degradation of pre-ribosomal RNA by the RNA exosome.
Synonyms: S9; uS4
Tractability: Small molecule: an approved drug acts on it; a structure with a bound ligand is known; a high-quality ligand is known. PROTAC: UniProt records ubiquitination sites on it; ubiquitination databases record sites on it; its protein half-life has been measured; a small molecule that binds it is known. Other modalities: a drug acting on it is in phase 2 or 3 trials.
Target class: Other cytosolic protein
Gene: Protein-coding gene on chromosome 19 (54,200,484 to 54,249,003, forward strand). Ensembl gene ENSG00000170889.
Subcellular location: Cytoplasm; Nucleus, nucleolus
Pathways (Reactome):
Metabolism of proteins: Eukaryotic Translation Termination; Formation of a pool of free 40S subunits; Formation of the ternary complex, and subsequently, the 43S complex; GTP hydrolysis and joining of the 60S ribosomal subunit; L13a-mediated translational silencing of Ceruloplasmin expression; PELO:HBS1L and ABCE1 dissociate a ribosome on a non-stop mRNA; Peptide chain elongation; Ribosomal scanning and start codon recognition; SRP-dependent cotranslational protein targeting to membrane; Translation initiation complex formation; ZNF598 and the Ribosome-associated Quality Trigger (RQT) complex dissociate a ribosome stalled on a no-go mRNA
Metabolism of RNA: Major pathway of rRNA processing in the nucleolus and cytosol; Nonsense Mediated Decay (NMD) enhanced by the Exon Junction Complex (EJC); Nonsense Mediated Decay (NMD) independent of the Exon Junction Complex (EJC); rRNA modification in the nucleus and cytosol
Disease: SARS-CoV-1 modulates host translation machinery; SARS-CoV-2 modulates host translation machinery; Viral mRNA Translation
Cellular responses to stimuli: Response of EIF2AK4 (GCN2) to amino acid deficiency
Developmental Biology: Regulation of expression of SLITs and ROBOs
Metabolism: Selenocysteine synthesis
Gene Ontology:
Molecular function: protein binding; RNA binding; structural constituent of ribosome; rRNA binding
Biological process: cytoplasmic translation; ribosomal small subunit biogenesis; translation
Cellular component: cytoplasm; cytosolic ribosome; cytosolic small ribosomal subunit; extracellular exosome; focal adhesion; membrane; nucleolus; nucleus; ribonucleoprotein complex; small-subunit processome; cytosol; nucleoplasm; ribosome; small ribosomal subunit; synapse
Genetic constraint (gnomAD): Loss-of-function variants: 1 observed, 17.93 expected, observed/expected ratio (o/e) 0.0558, 90% interval 0.019 to 0.26. The upper end of that interval is the gene's LOEUF score, 0.26, which puts it in group 1 of 6, group 1 being the genes least tolerant of losing a copy. Missense variants: 137 observed, 279.74 expected, observed/expected ratio (o/e) 0.49, 90% interval 0.43 to 0.56. Synonymous variants: 106 observed, 111.98 expected, observed/expected ratio (o/e) 0.95, 90% interval 0.81 to 1.11.
Homologues: Orthologues: chimpanzee RPS9 (100% identical), dog TFPT (100% identical), guinea pig RPS9 (100% identical), macaque RPS9 (100% identical), mouse Rps9 (100% identical), pig RPS9 (100% identical), rat LOC120097492 (95% identical), zebrafish rps9 (95% identical), Drosophila melanogaster RpS9 (86% identical), Caenorhabditis elegans rps-9 (79% identical).